PCDHGC3 (protocadherin gamma subfamily C, 3)
Description:
Potential calcium-dependent cell-adhesion protein. May be involved in the establishment and maintenance of specific neuronal connections in the brain.
Synonyms: PCDH-gamma-C3; PC-43; PCDH2; PC43
Tractability: Antibody: UniProt places it where antibodies can reach, with medium confidence; UniProt predicts a signal peptide or a membrane-spanning region; its Gene Ontology location is reachable by antibodies, with medium confidence; the Human Protein Atlas places it where antibodies can reach. PROTAC: its protein half-life has been measured.
Gene: Protein-coding gene on chromosome 5 (141,475,947 to 141,512,977, forward strand). Ensembl gene ENSG00000240184.
Subcellular location: Cell membrane
Subcellular location (Human Protein Atlas): Plasma membrane
Gene Ontology:
Molecular function: cell adhesion molecule binding; calcium ion binding
Biological process: calcium-dependent cell-cell adhesion; cell adhesion; homophilic cell-cell adhesion
Cellular component: membrane; plasma membrane
Genetic constraint (gnomAD): Loss-of-function variants: 26 observed, 62.61 expected, observed/expected ratio (o/e) 0.42, 90% interval 0.3 to 0.58. The upper end of that interval is the gene's LOEUF score, 0.58, which puts it in group 2 of 6, group 1 being the genes least tolerant of losing a copy. Missense variants: 1,080 observed, 1,309.3 expected, observed/expected ratio (o/e) 0.82, 90% interval 0.78 to 0.87. Synonymous variants: 487 observed, 563.62 expected, observed/expected ratio (o/e) 0.86, 90% interval 0.8 to 0.93.
Homologues: Orthologues: mouse Pcdhgc3 (92% identical). Paralogues in human: PCDHGA4 (48% identical), PCDHGA11 (48% identical), PCDHGA10 (48% identical), PCDHGA6 (48% identical), PCDHGB2 (47% identical), PCDHGC5 (47% identical), PCDHGC4 (47% identical), PCDHGA3 (47% identical), PCDHGA9 (46% identical), PCDHGA7 (46% identical), PCDHGA8 (46% identical), PCDHGA1 (46% identical), and 49 more.
Diseases named in the same sentence as PCDHGC3 in open-access papers:
PCDHGC3 is named in the same sentence as 22 diseases in open-access papers, as found by Europe PMC text mining. Sharing a sentence is not in itself a finding about the gene and the disease. The quoted sentences say what the papers report.
melanoma (6 papers, 2021 to 2026). A malignant, usually aggressive tumor composed of atypical, neoplastic melanocytes. "Although changes in mRNA expression of genes involved in metastasis, angiogenesis and cell adhesion were found in PCDHGC3 KO breast cancer and melanoma cells, the number of genes with significantly increased mRNA expression was higher in A2058 KO cells than in HCC1806 KO cells." (PMID 42042628, 2026). "Previous RNA expression data of PCDHGC3, generated from the database of the “The Cancer Genome ATLAS” (TCGA) project, indicated increased expression in gliomas and melanomas." (PMID 35897674, 2022). "Therefore, we generated a PCDHGC3 knockout (KO) in the triple-negative breast cancer cell line HCC1806 and the malignant melanoma cell line A2058." (PMID 42042628, 2026). "PCDHGC3, however, is barely expressed in normal melanocytes but is highly expressed in melanoma, therefore the cadherin family members are not exclusively downregulated or lost in melanoma." (PMID 34439879, 2021). "The mRNA expression data of TCGA revealed increased PCDHGC3 mRNA expression in gliomas (regardless of the WHO grade) and melanomas." (PMID 35897674, 2022).
breast carcinoma (3 papers, 2009 to 2026). "In a Wilms tumor, a malignant tumor of the kidney, and in prostate cancer, the PCDHGC3 promoter was found unmethylated, while in breast cancer, hypermethylation of the PCDHGC3 promoter occurs, which leads to suppressed expression." (PMID 35897674, 2022). "Also individual genes within an LRES region can show tumour-type specific changes, illustrated by PCDHGC3 which is frequently hypermethylated in breast cancer but which escapes methylation in WTs." (PMID 19956686, 2009).
glioma (1 paper, 2022). A benign or malignant brain and spinal cord tumor that arises from glial cells (astrocytes, oligodendrocytes, ependymal cells). "Nevertheless, the Wilcoxon Mann–Whitney test revealed an association of PCDHGC3 and the OS of patients with gliomas grade 2/3 (p = 0.022)." (PMID 35897674, 2022). "However, for glioma grade 2/3 patients, a significant association between PCDHGC3 mRNA expression level and OS was found when the Wilcoxon-Mann-Whitney test was used (p = 0.022)." (PMID 35897674, 2022). "We therefore tested widely used glioma cell lines GaMG, U87, U138, and U343 for PCDHGC3 protein expression." (PMID 35897674, 2022). "For the first time, we analyzed PCDHGC3 expression in gliomas under consideration of their WHO grading." (PMID 35897674, 2022). "High PCDHGC3 mRNA expression correlated with longer progression-free survival (PFS) in glioma patients." (PMID 35897674, 2022). "PCDHGC3 mRNA overexpression was found in gliomas grade 2/3 (median 8.41-fold, p < 0.001) and GBM (median 4.29-fold, p = 0.005) compared to non-cancerous brain samples." (PMID 35897674, 2022). "If one looks at the medians of the GBM and gliomas grade 2/3 subgroups, it can be seen that these are very close to each other, pointing to a similar PCDHGC3 expression." (PMID 35897674, 2022). "PCDHGC3 expression should therefore be further investigated as a PFS-marker in gliomas." (PMID 35897674, 2022). "Therefore, further experiments should clarify whether the Wnt signaling pathway is downregulated in PCDHGC3 overexpressing gliomas and whether the silencing of PCDHGC3 would lead to increased tumor growth, as has been shown for PCDH8." (PMID 35897674, 2022). "Therefore, the aim of this study was to examine PCDHGC3 expression in patient samples of gliomas with different WHO grades and to compare them with clinical parameters to determine whether the PCDHGC3 expression may serve as a prognostic biomarker." (PMID 35897674, 2022). "The expression data from this work show for the first time that gliomas exhibited increased PCDHGC3 mRNA expression compared to non-cancerous brain samples." (PMID 35897674, 2022). "These similar medians also indicate that the expression of PCDHGC3 did not correlate to the size or tendency to the multifocal growth of the gliomas examined, nor to any of the other clinical characteristics." (PMID 35897674, 2022). "Here, we examined the mRNA expression of PCDHGC3, a member of the PCDHγ cluster, in non-cancerous brain tissue and in gliomas of different World Health Organization (WHO) grades and correlated it with the clinical data of the patients." (PMID 35897674, 2022). "We showed that PCDHGC3 mRNA and protein were significantly overexpressed in glioma tissue compared to a non-cancerous brain specimen." (PMID 35897674, 2022). "The overexpression of PCDHGC3 in gliomas grade 2/3 and GBM compared to non-cancerous brain samples was analyzed on both the mRNA and protein level." (PMID 35897674, 2022). "The OS of GBM and gliomas grade 2/3 patients was not dependent on PCDHGC3 mRNA expression." (PMID 35897674, 2022). "Therefore, we were not able to determine glioma subgroups of high or low PCDHGC3 mRNA expression and concluded that PCDHGC3 serves no value as a predictive biomarker for these characteristics." (PMID 35897674, 2022).
Hypoglycemia (1 paper, 2020). A decreased concentration of glucose in the blood. "We provide the first evidence for PcdhgC3-mediated regulation of signaling pathways in BMECs and a changed inflammatory or hypoxia/hypoglycemia response." (PMID 33390965, 2020).
ovarian carcinoma (1 paper, 2022). A malignant neoplasm originating from the surface ovarian epithelium. "The other cancers analyzed, such as thyroid, lung, colorectal, head and neck, stomach, liver, and ovarian cancer, displayed very low PCDHGC3 expression." (PMID 35897674, 2022).
paraganglioma (1 paper, 2023). A benign or malignant neoplasm arising from paraganglia located along the sympathetic or parasympathetic nerves. "PCDHGC3 has been indicated as a potential biomarker, to identify individuals with paragangliomas and pheochromocytomas with an increased risk of metastasis." (PMID 37098643, 2023).
tumor (8 papers, 2001 to 2026). "By elucidating the tumor-suppressive role of PCDHGC3, this study expands our understanding of clustered PCDH biology and offers novel insights for ccRCC management." (PMID 41888110, 2026). "Here, we identified PCDHGC3 as a critical tumor suppressor, whose downregulation drives ccRCC aggressiveness." (PMID 41888110, 2026). "This is also supported by tumour-type specific variations in hypermethylation such as observed for PCDHGC3." (PMID 19956686, 2009). "The PCDHGC3 mRNA expression did not correlate with sex, MGMT promoter methylation, overall survival, tumor growth pattern, localization of tumor, tumor volume, Ki-67-staining, or type of therapy in GBM." (PMID 35897674, 2022).
cancer (6 papers, 2019 to 2026). A tumor composed of atypical neoplastic, often pleomorphic cells that invade other tissues. "EDA, SEMA3G, ENPP5, EMX2, and OPCML were favorable factors and had low expression levels in ccRCC tissues, whereas PCDHGC3 was a risk factor and highly expressed in cancer tissues." (PMID 36505496, 2022). "Recent reports indicate that the adhesion molecule protocadherin γ C3 (PCDHGC3) is differentially expressed in various cancer cells and endothelial cells of the blood-brain barrier (BBB), suggesting its involvement in the development of brain metastases." (PMID 42042628, 2026). "By contrast, PCDHGC3 expression increased in the cancer tissues." (PMID 36505496, 2022). "Interestingly, PCDHGC3 has been found highly methylated only in carcinomas and not in previous stages and has been proposed as a driver for the progression from adenoma to carcinoma." (PMID 31288858, 2019).
PCDHGC3 also shares sentences with these, for which no sentence is quoted: Arboleda-Tham syndrome (1 paper); brain tumors (1); breast invasive carcinoma (1); clear cell renal cell carcinoma (1); glioblastoma (1); leiomyosarcoma (1); malignant tumor of the kidney (1); neurological disorders (1); pheochromocytoma (1); prostate carcinoma (1); Sotos syndrome (1); triple-negative breast carcinoma (1); Weaver syndrome (1); Wilms tumor (1).